MT1P1 (metallothionein 1 pseudogene 1)
Synonyms: bA435O5.3
Gene: Processed pseudogene on chromosome 9 (95,413,267 to 95,413,449, reverse strand). Ensembl gene ENSG00000213761.
Diseases named in the same sentence as MT1P1 in open-access papers:
MT1P1 is named in the same sentence as 1 disease in open-access papers, as found by Europe PMC text mining. Sharing a sentence is not in itself a finding about the gene and the disease. The quoted sentences say what the papers report.
infection (1 paper, 2025). The state of being infected such as from the introduction of a foreign agent such as serum, vaccine, antigenic substance or organism. "In contrast, the ZIKVPE243 infection resulted in a lower number of significantly dysregulated genes, though a few exhibited large fold changes, including MD1, MT1P1, and FOSB." (PMID 41477009, 2025).